Y_RNA (Y RNA )
Gene: Miscellaneous RNA gene on chromosome 4 (55,501,595 to 55,501,708, reverse strand). Ensembl gene ENSG00000238585.
Homologues: Orthologues: chimpanzee Y_RNA (98% identical), macaque Y_RNA (94% identical). Paralogues in human: RNY1 (83% identical), RNY1P11 (83% identical), Y_RNA (83% identical), Y_RNA (82% identical), Y_RNA (81% identical), RNY1P10 (80% identical), RNY1P13 (80% identical), Y_RNA (80% identical), RNY1P8 (79% identical), Y_RNA (79% identical), Y_RNA (78% identical), RNY1P7 (77% identical), and 92 more.